LEP (leptin)
Diseases named in the same sentence as LEP in open-access papers (continued):
Sharing a sentence is not in itself a finding about the gene and the disease.
breast cancer (continued). "The farnesoid X receptor (FXR) has complex and contradictory functions in breast cancer regulation, but it has been shown that activation of this receptor inhibits leptin-induced breast cancer progression and motility." (PMID 33006013, 2020). "One of the suspected pathophysiological mechanisms by which excess adiposity promotes breast cancer is through the release of leptin from adipocytes." (PMID 33019728, 2020). "Given this dichotomy between the physiological and pathophysiological functions of CXCR4, we examined CXCR4 expression in breast cancer cells and found that it was upregulated by leptin." (PMID 32836215, 2020). "Breast cancer cells have been reported to secrete various adipokines, such as leptin, adiponectin, ATX, COX-2/PEG2, MMP, cathepsin K, TGF- β, IGF1 and VEGF (review)." (PMID 32674405, 2020). "Our results have a bioinformatics-based component and an in vitro-based component to gain insight into the interplay between FGFR1, leptin, and adiposity in breast cancer." (PMID 33019728, 2020). "Leptin stimulates growth, migration, and invasion of breast cancer via its pro-inflammatory effect, whereas adiponectin is an anti-inflammatory factor and is inversely associated with adiposity." (PMID 33108715, 2020). "There is a plethora of evidence that leptin induces cell migration and invasion in breast cancer via JAK/STAT3 signaling." (PMID 33339340, 2020). "The treatment of breast cancer MCF-7 cell line with leptin leads to a remarkable increase in the expression of EMT markers (including vimentin and Snail) along with a downregulation of the epithelial marker E-cadherin." (PMID 33123472, 2020). "In order to study the relationship between leptin protein expression levels and serum leptin levels in the transgenic breast cancer mouse model, serum leptin levels were also measured." (PMID 32133259, 2020). "A different proliferative effect of leptin in breast cancer cells involves the leptin mediated upregulation of human telomerase reverse transcriptase (hTERT) activity and expression in a dose-dependent fashion also involving STAT3 phosphorylation." (PMID 31380268, 2019). "Here, we show leptin produced by obASCs increases expression of Serpine1 in TNBC promoting a metastatic breast cancer phenotype." (PMID 31118047, 2019). "TEM analysis revealed that the number of MVBs in the cytoplasm of leptin-treated breast cancer cells was significantly increased compared to control cells." (PMID 31336913, 2019). "Recent evidence showed that leptin levels in the plasma are higher in breast cancer patients compared with healthy individuals." (PMID 31671408, 2019). "Other studies have demonstrated that estrogen receptor signaling plays a key role in leptin-induced growth of breast cancer cells via autophagy activation." (PMID 31380268, 2019). "It has been reported that leptin levels are increased in the plasma of breast cancer patients, which correlates with higher grade, advanced tumor stages, and aggressive subtypes." (PMID 31500658, 2019). "We found that leptin treatment enhanced the number of MVBs in the cytoplasm of breast cancer cells and increased the amount of exosomes released in cell conditioned media." (PMID 31336913, 2019). "A recent study discovered that HNK has anti-tumor activity; it can markedly inhibit the growth, invasion, and migration of breast cancer cells, and breast-tumor-xenograft growth induced by leptin." (PMID 31178721, 2019). "Of importance, exosomes derived from leptin-treated breast cancer cells display an higher levels of Hsp90, along with other leptin-related molecules such as HER2, pSTAT3, pJAK2 and pMAPK compared to exosomes released from vehicle-treated cells." (PMID 31336913, 2019). "This demonstrated that leptin can influence breast cancer cells not only by endocrine and/or paracrine actions, but also through autocrine pathways." (PMID 31380268, 2019).
breast cancer (continued). "Lately, the role of leptin and leptin receptor in breast cancer cells has shed light on the role of the adipose environment in breast cancer." (PMID 30823902, 2019). "Leptin, by binding to the leptin receptor (OB-R), promotes breast cancer cells to proliferate and develop." (PMID 31500658, 2019). "Adipocytes play crucial roles in the proliferation, survival, and invasion of breast cancer cells via secreting cytokines (including leptin, adiponectin and IL-6) or providing energy (such as fatty acids)." (PMID 31170987, 2019). "This study was designed to investigate the association between plasma leptin levels and CRF in a cohort of early‐stage breast cancer patients, in relation with other relevant clinical factors and adipokines." (PMID 31016867, 2019). "Leptin secreted by adipose-derived stem cells promotes the growth and metastasis of ER + breast cancer by increasing the expression of ER receptor and aromatase." (PMID 31440472, 2019). "In our cohort of early‐stage breast cancer patients, plasma leptin levels were found to be significantly and negatively correlated with total MFSI‐SF score across time points (β = −0.56, P < 0.01)." (PMID 31016867, 2019). "Both leptin and its specific receptor are overexpressed in breast cancer tissue, especially in higher-grade tumors, and are associated with distant metastasis." (PMID 31336913, 2019). "It has been demonstrated that leptin regulates the cell cycle and increases breast cancer cell growth by inducing cyclin D1 expression via STAT3 activation." (PMID 31380268, 2019). "Accumulated FFA, cholesterol, triglycerides, estrogen, leptin, insulin, interleukins, and chemokines together promote breast cancer initiation, proliferation, and invasion." (PMID 31398937, 2019). "The pooled and sub-group results of the serum leptin levels in breast cancer compared with the controls." (PMID 30702563, 2019). "C-peptide, insulin, leptin, and other metabolic hormones are assumed to play roles in breast cancer development; though, results are inconsistent." (PMID 31292496, 2019). "In general, in the cultures of the three different breast cancer cell lines, a positive proliferative effect was observed by stimulation with leptin, the opposite effect was observed when stimulating with tamoxifen." (PMID 31844100, 2019). "Women that were diagnosed with estrogen receptor/progesterone receptor positive (ER+/PR+) breast cancers that also expressed high levels of leptin had poorer prognosis than women with low leptin expression." (PMID 31013744, 2019). "Targeting leptin signaling, by a selective leptin receptor antagonist the peptide LDFI (Leu-Asp-Phe-Ile), abrogated leptin effects on Tsg101 expression and on exosome secretion in breast cancer cells." (PMID 31336913, 2019). "Among these molecules, leptin is one of the most important adipokines involved in the development and progression of mammary tumors." (PMID 31671408, 2019). "Specific inhibitors of FAK, Src and STAT3 showed that the effect exerted by leptin in cell migration in breast cancer cells is dependent on these proteins." (PMID 31671408, 2019). "Leptin has been suggested to induce CYP1B1 expression in ERα-positive breast cancer cells in a mechanism that involves AKT and ERK signaling pathways." (PMID 31380268, 2019). "Despite the role of cAMP and leptin, respectively, as growth suppressor and growth promoting factors in breast cancer cells, an antiproliferative interaction between leptin and cAMP elevation has been described." (PMID 31380268, 2019). "Adiponectin has been shown to counteract the effect of leptin by inhibiting leptin-induced migration and invasion in breast cancer in addition to leptin-induced clonogenicity and anchorage independent cell growth." (PMID 31121868, 2019).
breast cancer (continued). "In this study, we have provided an additional role for this adipokine in breast cancer biology since we have found that leptin is able to regulate exosome biogenesis and release in different models of breast cancer cells." (PMID 31336913, 2019). "Particularly, this crosstalk represents the integration of developmental, pro-inflammatory and pro-angiogenic signals critical for leptin-induced cell proliferation, migration, angiogenesis and self-renewal of breast cancer stem cells (CSCs)." (PMID 30634494, 2019). "It is known that excessive free fatty acids, cholesterol, triglycerides, hormones, leptin, interleukins, and chemokines upregulate breast cancer development." (PMID 31398937, 2019). "The primary objective of this study was to evaluate the association between leptin and CRF in early‐stage breast cancer patients receiving chemotherapy." (PMID 31016867, 2019). "Women that were diagnosed with estrogen receptor/progesterone receptor positive (ER+/PR+) breast cancers (BC) that also expressed high levels of leptin had poorer prognosis than women with low leptin expression." (PMID 31208047, 2019). "Specifically, it has been proposed that PI3K/AKT regulates leptin mediated-epithelial mesenchymal transition in breast cancer." (PMID 31380268, 2019). "Both STAT3 activation and ERK1/ERK2 signaling mediated by leptin have been described to act as a key event in ERα-dependent development of breast cancer." (PMID 31380268, 2019). "It has been shown that leptin promotes the development and progression of breast cancer neoplastic cells by activating the JAK2/STAT3 pathway." (PMID 31380268, 2019). "Our observations at electron microscope level revealed that leptin treatment significantly increased the number of MVBs in the cytoplasm of breast cancer cells and the amount of exosomes released in the conditioned media of cells." (PMID 31336913, 2019). "Our group has previously reported that ASCs from human lipoaspirate from obese donors (BMI > 30) promote tumor growth and metastasis in ER+ breast cancer through, at least in part, a leptin-estrogen pathway." (PMID 31118047, 2019). "In this line, recent data from human breast-cancer-studies suggest that leptin-activated STAT3, also promotes cancer cell stemness and chemoresistance through the expression of critical enzymes for acid β-oxidation pathways." (PMID 31380268, 2019). "On the other hand, other studies have suggested a role for the protein BMP9 as a negative regulator of leptin expression in breast cancer cells." (PMID 31380268, 2019). "In contrast to leptin, adiponectin decrease proliferation and stimulate the cell death program in breast cancer cells by several pathways including AMP-activated protein kinase, mTOR, and NF-κB pathways." (PMID 31398937, 2019). "In another trial, a decrease in leptin concentrations in breast cancer survivors who exercised compared to controls was reported." (PMID 31016867, 2019). "High levels of leptin and overexpression of its receptors in obese women can lead to an increase in signaling, key in the development of breast cancer." (PMID 31380268, 2019). "Niu and collaborators conducted a meta-analysis including pre- and postmenopausal breast cancer women and healthy controls, as well as lymph node metastasis positive cases, and concluded that leptin levels play a role in breast cancer." (PMID 30823902, 2019). "For instance, the NLRP3 inflammasome was involved in leptin-induced growth of breast cancer cells via promotion of cell cycle progression and suppression of cell apoptosis." (PMID 31492049, 2019). "In conclusion, our data show that there is an inverse correlation between plasma leptin levels and fatigue levels over time in early‐stage breast cancer patients undergoing chemotherapy." (PMID 31016867, 2019). "Adipocytokine leptin has been shown to turn on an oncogenic signaling cascade and stimulate breast cancer growth in obese state." (PMID 31618928, 2019).
breast cancer (continued). "Increased leptin, which upregulates estrogen receptor alpha (ERα) and aromatase, enhances estrogen bioavailability and signaling in estrogen receptor positive (ER+) breast cancer (BC) tumor growth and metastasis." (PMID 30897853, 2019). "Quantification of breast cancer cell migration to leptin shRNA obASCs compared to control shRNA obASCs demonstrated that breast cancer had decreased migratory ability when leptin was knocked down in obASCs." (PMID 31118047, 2019). "Regarding regulation of leptin expression in breast carcinogenesis, it is remarkable that hyperinsulinemia induces breast cancer progression also through leptin-expression-dependent mechanisms." (PMID 31380268, 2019). "A positive association between leptin expression, LEPR, aromatase and MAPK and STAT3 activation has been suggested using tissue samples of patients with estrogen receptor positive breast cancer." (PMID 31380268, 2019). "Different studies have reported an interplay between leptin and different members of growth factor family, resulting in an enhanced growth and metastatic properties of breast cancer cells." (PMID 30634494, 2019). "Leptin network relationships have been correlated to prognosis and also pharmacological responses in some follow-up studies of breast cancer." (PMID 31380268, 2019). "Other receptors have been proposed to be functionally important mediating the actions of leptin in breast cancer." (PMID 31380268, 2019). "As another example of this point of convergence with TGFβ signaling, leptin has been involved in metastasis and recurrence of breast cancer, likely participating in the inhibition of acetil CoA carboxylase 1 (ACC1)." (PMID 31380268, 2019). "Apart from this, events that promote leptin negative regulation are emerging as novel therapeutic targets for patients with breast cancer." (PMID 31380268, 2019). "In line with the “in vivo” findings, a growing body of experimental “in vitro” evidence clearly demonstrated the multifaceted role of leptin in supporting the oncogenic phenotype of breast cancer." (PMID 30634494, 2019). "Recently, a novel mechanism has been proposed for the role of leptin in breast cancer progression in ER-α positive cells." (PMID 31380268, 2019). "Leptin activates ERα to stimulate estrogen-related breast cancer pathway, resulting in the proliferation and migration." (PMID 31398937, 2019). "We have accumulating reports from studies in breast cancer cell lines that show the active participation of leptin in proliferation and anchorage-independent propagation of breast tumor." (PMID 30881358, 2019). "Our data showed that in two breast cancer cellular models, leptin induces an increase in MMPs secretion and activation in a time and dose response-dependent manner." (PMID 31671408, 2019). "Our findings strongly suggest that leptin promotes the development of a more aggressive invasive phenotype in mammary cancer cells." (PMID 31671408, 2019). "RT-qPCR of breast cancer cells after 3 days of transwell co-culture with control shRNA obASCs or leptin shRNA obASCs shows an increase in expression of CCL5, CD90, PTGS2, and IL-6 after co-culture with obASCs that is abrogated by leptin shRNA in the obASCs." (PMID 31118047, 2019). "By employing these genetically modified breast cancer cells (BCCs), the effect(s) obASCs have on ER+BC outside of the ERα-leptin signaling axis can be investigated." (PMID 30897853, 2019). "Overall, our results identify for the first time leptin/leptin receptor/Hsp90 axis as an important regulator of exosome generation in mammary carcinoma cells." (PMID 31336913, 2019). "In cocultured adipocytes, leptin mRNA expression was significantly decreased, while in cocultured breast cancer cells, leptin mRNA expression was significantly increased." (PMID 30563531, 2018). "Leptin plays an important role in breast cancer progression due to the biological processes it participates in, such as epithelial–mesenchymal transition (EMT)." (PMID 30404206, 2018).
breast cancer (continued). "In in vitro models, such as MCF7, MDA-MB-231, and SK-BR-3 breast cancer cells, leptin activates signaling pathways that promote proliferation, cell migration, invasion, and epithelial–mesenchymal transition (EMT)." (PMID 30404206, 2018). "Our results demonstrated that, of the adipocyte-derived adipokines, IL-6 and leptin were highly expressed after coculture with breast cancer cells." (PMID 30563531, 2018). "Cytoplasmic immunohistochemical staining of leptin was less detected in breast cancer with poor survival." (PMID 29682217, 2018). "Under an obese state in breast cancer, leptin interacts with molecular effectors such has estrogen, insulin, IGF-1 and inflammatory cytokines, which impacts various stages of breast cancer from initiation to metastatic progression." (PMID 30567335, 2018). "Guo and Gonzalez-Perez described a novel crosstalk between Notch, IL-1, and leptin that induces angiogenesis in breast cancer." (PMID 29915603, 2018). "This metabolic leptin-induced reprogramming confers benefits to tumor cells and a greater aggressiveness to breast cancer cells." (PMID 30404206, 2018). "Based on our qRT-PCR results, we next detected levels of secreted IL-6 and leptin in the medium of 3 T3-L1 preadipocytes, adipocytes and adipocytes cocultured with breast cancer cells." (PMID 30563531, 2018). "Animal and cell studies found that close proximity between adipocytes and breast cancer cells is required for tumor growth and their interaction depended on adipose tissue aromatase expression through leptin signaling." (PMID 30567335, 2018). "When co-cultured with ASCs from obese models, breast cancer cells showed enhanced survival and radioresistance in part through leptin signaling." (PMID 30567335, 2018). "We next examined the expression of PLOD2 following treatment of MDA-MB-231 and MDA-MB-468 breast cancer cells with leptin." (PMID 30563531, 2018). "The relative leptin expression level is highly found in bladder cancer, breast cancer, large B cell lymphoma, lung cancer, ovarian cancer, pancreatic cancer, testicular cancer." (PMID 29682217, 2018). "A novel and complex signaling crosstalk between leptin, Notch and IL-1 (Notch, IL-1 and leptin crosstalk outcome, NILCO) seems to drive leptin-induced oncogenic actions in breast cancer." (PMID 30004402, 2018). "We observed that treatment with recombinant human leptin resulted in a significant increase in PLOD2 expression in breast cancer cells in a time-dependent manner." (PMID 30563531, 2018). "The practice of physical exercises has been highlighted as an important protective factor against breast cancer, since it reduces serum levels of estrogen, insulin, leptin, and proinflammatory cytokines and increases adiponectin." (PMID 30112392, 2018). "Tx, a standard hormone therapy, increases serum leptin levels in postmenopausal breast cancer patients." (PMID 29389973, 2018). "In breast cancer cells, leptin and transforming growth factor β (TGFβ) co-regulate AMPK-mediated ACC phosphorylation, implying that FAO is also affected by these signals." (PMID 29996946, 2018). "Leptin increases the synthesis of pro-inflammatory cytokines and plays a role in breast cancer development by increasing cellular proliferation and angiogenesis." (PMID 30619088, 2018). "Taken together, these results indicate that leptin suppresses CCN5 expression in ER-α-positive breast cancer cells at the transcription level." (PMID 29370782, 2018). "Expression of IL-6 increased while leptin expression decreased when adipocytes were cocultured with MDA-MB-231 breast cancer cells." (PMID 30563531, 2018). "cAMP elevation also displayed the inhibitory effect to leptin-induced breast cancer MDA-MB-231 migration which was accompanied by a strong decrease of β3 integrin subunit and focal adhesion kinase (FAK) protein levels." (PMID 29682217, 2018).